H2AC25 (H2A clustered histone 25)
Description:
Core component of nucleosome. Nucleosomes wrap and compact DNA into chromatin, limiting DNA accessibility to the cellular machineries which require DNA as a template. Histones thereby play a central role in transcription regulation, DNA repair, DNA replication and chromosomal stability. DNA accessibility is regulated via a complex set of post-translational modifications of histones, also called histone code, and nucleosome remodeling.
Synonyms: H2AW; HIST3H2A; MGC3165
Tractability: PROTAC: UniProt records ubiquitination sites on it; ubiquitination databases record sites on it.
Gene: Protein-coding gene on chromosome 1 (228,434,777 to 228,457,873, reverse strand). Ensembl gene ENSG00000181218.
Subcellular location: Nucleus; Chromosome
Subcellular location (Human Protein Atlas): Nucleoplasm
Pathways (Reactome):
Chromatin organization: HATs acetylate histones; HDACs deacetylate histones; RMTs methylate histone arginines
Disease: Dengue Virus-Host Interactions; HCMV Early Events; HCMV Late Events
Metabolism of proteins: Metalloprotease DUBs; UCH proteinases; Ub-specific processing proteases
Gene Ontology:
Molecular function: DNA binding; protein binding; structural constituent of chromatin; protein heterodimerization activity
Biological process: nucleosome disassembly; UV-damage excision repair; heterochromatin formation
Cellular component: extracellular exosome; nucleoplasm; nucleosome; chromosome; nucleus
Genetic constraint (gnomAD): Loss-of-function variants: 5 observed, 5.95 expected, observed/expected ratio (o/e) 0.84, 90% interval 0.44 to 1.67. That is too few expected variants to judge how well the gene tolerates losing a copy. Missense variants: 168 observed, 205.4 expected, observed/expected ratio (o/e) 0.82, 90% interval 0.72 to 0.93. Synonymous variants: 100 observed, 98.73 expected, observed/expected ratio (o/e) 1.01, 90% interval 0.86 to 1.2.
Homologues: Orthologues: chimpanzee H2AC25 (100% identical), mouse H2ac25 (100% identical), pig H2AC25 (100% identical), rat H2ac25 (100% identical), dog H2AC25 (99% identical), Drosophila melanogaster His2A:CG31618 (85% identical), Drosophila melanogaster His2A:CG33808 (85% identical), Drosophila melanogaster His2A:CG33814 (85% identical), Drosophila melanogaster His2A:CG33817 (85% identical), Drosophila melanogaster His2A:CG33820 (85% identical), Drosophila melanogaster His2A:CG33823 (85% identical), Drosophila melanogaster His2A:CG33826 (85% identical), and 13 more. Paralogues in human: H2AC4 (99% identical), H2AC6 (99% identical), H2AC8 (99% identical), H2AC7 (98% identical), H2AC11 (98% identical), H2AC13 (98% identical), H2AC15 (98% identical), H2AC16 (98% identical), H2AC17 (98% identical), H2AC18 (98% identical), H2AC19 (98% identical), H2AC12 (96% identical), and 15 more.
Diseases named in the same sentence as H2AC25 in open-access papers:
H2AC25 is named in the same sentence as 11 diseases in open-access papers, as found by Europe PMC text mining. Sharing a sentence is not in itself a finding about the gene and the disease.
H2AC25 shares sentences with these, for which no sentence is quoted: tumor (6 papers); lung cancer (3); non-small cell lung carcinoma (3); pancreatic cancer (3); glioblastoma (2); prostate carcinoma (2); asthma (1); breast carcinoma (1); cancer (1); hepatocellular carcinoma (1); systemic lupus erythematosus disease (1).